LCN2 (lipocalin 2)
Diseases named in the same sentence as LCN2 in open-access papers (continued):
Sharing a sentence is not in itself a finding about the gene and the disease.
tumor (continued). "Second, it increases the expression of LCN2, a high-affinity iron-binding protein critical for iron export from tumor-associated macrophages, by activating endoplasmic reticulum stress in these cells." (PMID 39850877, 2024). "LCN2 is an important lipocalin that is frequently associated with tumor size, stage, and invasiveness in multiple cancers." (PMID 38673873, 2024). "High expression of Lcn-2 in cancerous tissues of the thyroid, ovarian, breast, prostate, pancreatic, renal, and colorectal organs underline the tumor-promoting role of Lcn-2." (PMID 37958332, 2023). "This review aims to summarize the current knowledge about OC, FGF23, SCL, and LCN2 and to characterize the association between them and tumor bone metastasis." (PMID 36926025, 2023). "A higher expression level of LCN2 is usually associated with tumour size, tumour stage, and invasion of carcinoma cells, and indicates a poor prognosis." (PMID 37753805, 2023). "The interaction of LCN2 with MMP9 is associated with the invasive behaviour of several tumour cells." (PMID 37060578, 2023). "Macrophage polarization is closely associated with the differential regulation of iron metabolism, whereby an increase in TAM’s Lcn-2 expression causes an iron release phenotype that supports tumor growth and therapy resistance." (PMID 37958332, 2023). "LCN2, also known as neutrophil gelatinase–associated lipocalin, was first identified in 1993; it is a secretory protein that can regulate immunity and tumor progression." (PMID 38072118, 2023). "Recently, an immunohistochemical analysis of NPC tumor specimens demonstrated that LCN2 expression is associated with the survival of NPC patients." (PMID 36428800, 2022). "High prostatic tissue LCN2 expression is associated with significantly reduced tumor differentiation and higher Gleason scores in PCa patients." (PMID 35406450, 2022). "While the importance of the iron-load of lipocalin-2 (Lcn-2) in promoting tumor progression is widely appreciated, underlying molecular mechanisms largely remain elusive." (PMID 34069743, 2021). "Since we previously determined that the iron-load of Lcn-2 plays a critical role for its pro-tumor functions in RCC, we now aimed to identify underlying molecular mechanisms." (PMID 34069743, 2021). "More specifically, the activation of NF-kB in tumor cells enhances the expression of several genes (including Ccl7, Cxcl1, Ccl5, Slc39a10, Lcn2, Zc3h12a, and Enpp2) that are implicated in tumor migration, angiogenesis, and formation of pre-metastatic niches." (PMID 33567747, 2021). "Recently, accumulating evidence has demonstrated that the LCN2 protein is implicated in a wide range of cellular and pathophysiological processes such as insulin insistence, tumor cell proliferation, and apoptosis." (PMID 34903175, 2021). "In vivo, LCN2 is involved in tumor lymphangiogenesis and its associated metastases since there are less lung metastases and lower lymphatic vessel density in PyMT LCN2 KO mice than those in WT mice." (PMID 33783686, 2021). "The role of Lcn-2 as an iron exporter has been mainly characterized in tumor-associated macrophages." (PMID 34829813, 2021). "LCN2 was positively associated with IDH-wt tumours (residuals = 2.84; P = 0.04), whereas LCN3 was negatively associated with IDH-mutated/1p19q-codeleted tumours (residuals = −3.39; P = 0.006)." (PMID 34917940, 2021). "There are also studies that indicate that LCN2 can be regulated and that it is associated with many signalling pathways in certain tumour cell models." (PMID 33277533, 2020). "Some studies have correlated upregulated LCN2 expression in tumor tissue with poor outcomes caused by increased growth of cancer cells, therapeutic resistance, invasion, and metastasis." (PMID 32575507, 2020). "The recently discovered tumor biomarker lipocalin-2 (Lcn2) was initially found to be associated with iron absorption, antimicrobial activity, and epithelial cell differentiation." (PMID 32154171, 2020).
tumor (continued). "Findings that high levels of LCN2 are associated with inhibition of tumor growth and proliferation are also discussed." (PMID 32575507, 2020). "In the univariate analysis, gain of the C1QL1 [odds ratio (OR) = 5.34; P = 0.006] and LCN2 (OR = 3.48; P = 0.029) expression were significantly associated with the extrathyroidal extension of the tumour." (PMID 29321030, 2018). "Whereas LCN2-deficient mice significantly reduced tumor cell dissemination into the lung, neutralizing LCN2 antibody resulted in significant blockage of lung metastasis." (PMID 29983888, 2018). "LCN2 is frequently associated with tumor size, stage, and invasiveness, involving in the invasion and poor prognosis of carcinoma cells." (PMID 29098164, 2017). "IL-6, IL-1β, and LCN2, previously associated with tumor growth and metastasis, were up-regulated in LuM cells." (PMID 28410227, 2017). "We describe how macrophages handle iron in the tumor microenvironment, discuss the relevance of an iron-release macrophage phenotype for tumor progression, and propose a new role for Lcn-2 in tumor-associated macrophages." (PMID 28979267, 2017). "Through transcriptome profiling and combined gain- and loss-of-function studies, we identified LCN2 as a major downstream effector of TCF7L1 that drives tumor growth." (PMID 28467300, 2017). "LCN2 is elevated in multiple human cancers, frequently being associated with tumor size, stage, and invasiveness." (PMID 29098164, 2017). "The results revealed that HK2 and LCN2 are associated with tumor progression, especially in LUSC tissue." (PMID 29285270, 2017). "Several possible molecular mechanisms underlying LCN2 functions in tumor progression have been demonstrated, including promotion of epithelial to mesenchymal transition (EMT) and modulation of matrix metallopeptidase (MMP)-9 activity." (PMID 26840566, 2016). "Several findings indicate that LCN2 overexpression is associated with tumor size, stage, and invasiveness, and it has been proposed as a negative prognostic indicator in several types of cancer." (PMID 27249794, 2016). "LCN2, also known as NGAL, encodes lipocalin 2, which is a neutrophil gelatinase-associated lipocalin that contributes to tumor progression." (PMID 24498386, 2014). "Together, our data supports the association of LCN2 expression and aggressive tumour growth by stimulating angiogenesis through the upregulation of HIF1A and VEGF." (PMID 23056397, 2012). "The total tumor volume and number of metastases were quantitated in 26 lipocalin-2-deficient mice and 34 wild-type controls." (PMID 22737251, 2012). "LCN2 expression in the primary tumor was significantly associated with pattern of tumor recurrence (p = 0.029), and LCN2 staining was especially related to the development of liver metastases (p = 0.008, Fisher exact test)." (PMID 22559235, 2012). "Next, LCN2 overexpression and knockdown cell lines were constructed via lentiviral vectors to perform gain- and loss-of-function experiments, demonstrating that LCN2 could serve as a tumor suppressor gene in CRC metastasis." (PMID 40313933, 2025). "Additionally, MAPK11 facilitates the upregulation of lipid transport protein 2 (LCN2), a factor linked to increased tumour development, invasion, and metastasis, thereby contributing to cancer progression." (PMID 40070022, 2025). "Tumor-associated macrophages (TAMs) are essential for maintaining iron homeostasis with the M2-phenotype in particular promoting tumor growth and resistance to therapy by releasing high levels of LCN2 in the TME, providing iron to cancer cells." (PMID 41303420, 2025). "LCN2 has been associated with tumour progression and metastasis and has been proposed as a non‐invasive prognostic indicator, although its precise role in BC remains unclear." (PMID 41363723, 2025). "We review the molecular mechanisms underlying the oncogenic and tumor-suppressive roles of LCN2." (PMID 40109857, 2025).
tumor (continued). "Therefore, Lcn-2, a transferrin-independent iron carrier, which tumor-associated macrophages (M2-phenotype) increase its expression in the more aggressive tumor environment, allows cancer cells to acquire the additional necessary iron." (PMID 40450119, 2025). "However, neutrophils in the gem group expressed high levels of CXCR2, LRG1, and LCN2 genes, which are associated with tumor progression and metastasis." (PMID 37324492, 2023). "The controlled release of LCN2 into the tumor microenvironment could cause effects on EGFR shuttling and on activation of EGFR by phosphorylation, as reported in a recent study." (PMID 35216088, 2022). "Hence, it is plausible to surmise that the increased tumor burden in the lungs following the loss of Lcn2 is closely associated with significant changes in the microbiome of the tumor’s microenvironment." (PMID 36142843, 2022). "Indeed, it has been shown that lipocalin-2 has pro-tumorigenic effects in experimental tumor models and its overexpression is associated with decreased survival in patients." (PMID 33804198, 2021). "However, LCN2's role in the VHL-mutation-mediated progression of tumor formation via the regulation of oxidative homeostasis and mitochondrial metabolism has not been previously studied." (PMID 34257811, 2021). "Some human cancers strongly express LCN2 associated with the tumor size and invasiveness." (PMID 34359830, 2021). "LCN2 is a glycoprotein of the lipocalin superfamily which could be secreted by adipocytes, immune cells and tumor cells and was suggested to be implicated in a variety of cancers." (PMID 32076707, 2020). "For instance, through the release of lipocalin-2, neutrophils can activate tumor cells via the phosphorylation of PI3K/Akt, causing the downstream expression of VEGF and HIF-1, which are factors important for tumor progression, angiogenesis, and chemoresistance." (PMID 33022971, 2020). "Besides cancer cells, lipocalin-2 can enhance the protumoral functions of tumor-associated stromal cells." (PMID 33679721, 2020). "Lipocalin-2 deficiency in TAM inhibits tumor growth, which can be reversed by iron supplement." (PMID 33679721, 2020). "In this research, data-mining analysis based on various databases, we comprehensively analyzed the expression of LCN2 and its association with tumor-infiltrating immune cells (TIICs) and related immune markers, and further visualized its prognostic landscape in pan-cancer." (PMID 33425761, 2020). "Moreover, LCN2 deficiency attenuated tumor development in a xenograft model including lung metastasis when inoculating MCF-7 cells pretreated with supernatants from wild-type and LCN2-knockdown macrophages." (PMID 28804221, 2017). "Both LCN2 and IL-1β are linked to lymphangiogenesis and tumor metastasis." (PMID 28804221, 2017). "To test whether LCN2 is a major downstream effector of TCF7L1 that stimulates tumor growth, we took a combined gain- and loss-of-function strategy." (PMID 28467300, 2017). "Furthermore, Lcn-2 coordinates the expression of vascular endothelial growth factor and causes the induction of angiogenesis in the tumor microenvironment." (PMID 28979267, 2017). "Interestingly, immunohistochemical analysis of CRC tissues showed that LCN2 was positively correlated with membrane E-cadherin and negatively associated with nuclear β-catenin, which are both critical factors in tumor initiation and progression." (PMID 27912767, 2016). "An association between LCN2 and tumor invasion/metastasis is documented." (PMID 25940797, 2015). "LCN2 has been reported to promote resistance to drug-induced apoptosis, enhance invasion through its physical association with matrix metalloproteinase-9, and promote in vivo tumor growth." (PMID 23056397, 2012).
tumor (continued). "While major differences in the role of lipocalin-2 on tumor progression and metastasis was observed in these two studies, both confirmed that lipocalin-2 is associated with tumor progression and that complex formation with MMP-9 seems to be part of the mechanism." (PMID 22737251, 2012). "Notably, LCN2 was significantly associated with distant tumor recurrences, as well as with the S100A family of metastasis related genes." (PMID 22559235, 2012). "It will be of great interest to determine whether such inhibitors suppress lipocalin-2 production from patient tumor-associated macrophages and neutrophils and reduce iron content in patient tumor cells and whether these effects contribute to the anticancer efficacy." (PMID 33679721, 2020). "Additionally, LCN2 overexpression and its iron-shuttling functions have been associated with the inhibition of apoptosis, which is essential for cancer cell survival in the tumor microenvironment (TME)." (PMID 32575507, 2020). "Additionally, experimental transgenic tumor-bearing mouse mammary tumor virus (PyMT) mice exhibit higher Lcn-2 plasma levels compared to controls, and Lcn-2-deficient PyMT mice developed fewer tumors than Lcn-2-competent littermates." (PMID 30641920, 2019). "Furthermore, the unmethylation of LCN2 was associated with malignant tumour characterisation and a poor prognosis, which may have resulted from the antitumour effect of vitamin D." (PMID 31819048, 2019). "In addition, gain of LCN2 expression in PTC was significantly associated with larger tumour size." (PMID 29321030, 2018). "The fact that these three cytokines (IL-6, IL-1β, LCN2) were up-regulated in LuM cells indicates that these highly metastatic cells obtained through in vivo selection will be a useful resource for further studies on elucidating the mechanisms underlying cytokine-related tumor growth and metastasis." (PMID 28410227, 2017). "In vivo, SATB2 overexpression inhibited xenograft tumor growth and lung metastasis, while LCN2 overexpression rescued these suppressive effects." (PMID 41736683, 2026). "Recent evidence has highlighted the pleiotropic roles of lipocalin 2 (LCN2) in promoting tumor cell proliferation, adhesion, and stress resistance." (PMID 42088941, 2026). "They further supply iron to tumor cells via lipocalin 2-mediated efflux 58-60, thereby fueling tumor growth." (PMID 41355954, 2026). "GO analysis also revealed activation of the tumor necrosis factor (TNF) and Janus kinase (JAK)-STAT signaling pathways in PC9-BM cells and in tumor cells with high LCN2 expression in clinical BM patient samples." (PMID 41436606, 2025). "Prior research has established that in BCa, H3K18la promotes tumor proliferation and migration by up-regulating LCN2 expression, and facilitates cisplatin resistance by enhancing the expression of YBX1 and YY1." (PMID 41199784, 2025). "We found that tumor-derived LCN2 activated astrocytes through SLC22A17 and JAK2/STAT3 signaling, leading to the secretion of macrophage-recruiting chemokines." (PMID 41436606, 2025). "In this study we evaluated the serum levels of transferrin and lipocalin 2 in Syrian breast cancer patients and compared them with those in a control group, and we also studied the correlation of their levels with the tumor status in patients." (PMID 40450119, 2025). "The analysis revealed activation of the inflammatory response and the IL6–JAK–STAT3 signaling pathways in tumor cells with high LCN2 expression." (PMID 41436606, 2025). "Brain metastatic tumor cells secrete LCN2, which binds to SLC22A17 on astrocytes, activating JAK2/STAT3 signaling and inducing astrocyte activation and chemokine secretion, thereby facilitating macrophage recruitment." (PMID 41436606, 2025). "These macrophages, in turn, secrete IL-1β, which upregulates LCN2 expression in tumor cells, establishing a paracrine feedback loop." (PMID 41436606, 2025).
tumor (continued). "Lipocalin 2 (LCN2) is an iron-binding acute-phase protein that plays critical roles in regulating cellular iron homeostasis, inflammatory responses, and tumor progression." (PMID 40636695, 2025). "NF-κB is a well-known transcription factor that upregulates LCN2 levels in tumor cells under inflammatory conditions and ER stress, but the regulation of LCN2 by ATF4 and STAT3 in tumor biology has not yet been reported." (PMID 40109857, 2025). "Research has largely focused on the tumor cell–intrinsic functions of LCN2, while its roles in cells of the adaptive immune system have received considerably less attention." (PMID 41303420, 2025). "Third, the role of microglia—brain-resident macrophages—in regulating LCN2 in BM tumor cells remains to be elucidated." (PMID 41436606, 2025). "Consistent with its expression pattern, LCN2 plays a tumor-suppressive role in the progression of tumors." (PMID 40109857, 2025). "LCN2 emerges as a pivotal secreted factor that links EGFRvIII expression in tumor cells to fibroblast activation, thereby driving stromal remodeling and contributing to OSCC progression." (PMID 40472740, 2025). "Here, we report efficient internalization of this formulation into HER2+ IBC cells, reducing LCN2 levels by 30% and disrupting tumor emboli formation." (PMID 40732340, 2025). "Within the brain parenchyma, LCN2 facilitates tumor colonization and growth by supporting neuroinflammation, modulating immune cell recruitment, and enhancing iron availability." (PMID 40732340, 2025). "They elucidated how LCN2 secreted by neutrophils promotes tumor progression under the influence of c-Met." (PMID 41303420, 2025). "We demonstrated that tumor-derived LCN2 activates astrocytes within metastatic foci, triggering macrophage recruitment." (PMID 41436606, 2025). "Strikingly, once tumor cells reach the brain parenchyma, LCN2 expression significantly enhances intracranial tumor growth (P < 0.05 and P < 0.01, respectively)." (PMID 41436606, 2025). "Our data further demonstrate that tumor-derived LCN2 plays a critical role in mediating EGFRvIII-induced fibroblast activation via the STAT3 signaling pathway." (PMID 40472740, 2025). "Consistently, elevated CCL2 levels were detected in supernatants from LCN2-high tumor cells cocultured with astrocytes but not in supernatants from tumor cells alone or from those cocultured with oligodendrocytes." (PMID 41436606, 2025). "Recent evidence indicates that, beyond TFR1 and DMT1, lipocalin-2 (LCN2, also called neutrophil gelatinase-associated lipocalin or NGAL) provides an alternative iron-delivery pathway that is exploited by multiple tumor types." (PMID 41190142, 2025). "LCN2 is significantly expressed in various tumors and plays an important role in regulating tumor cell proliferation, invasion, and metastasis." (PMID 40109857, 2025). "While we did not interrogate specific cell death mechanisms, it is possible that LCN2 knockdown triggered cell death pathways that compromised the internal structure of tumor emboli, leading to breakdown." (PMID 40732340, 2025). "In cancer cells, EGFRvIII has been shown to induce LCN2 expression, thereby promoting tumor cell invasion, immune suppression, and the recruitment of immunosuppressive cell types." (PMID 40472740, 2025). "LCN2 is critical for tumor growth, epithelial-to-mesenchymal transition, angiogenesis, and cell proliferation because it forms complexes with matrix metalloproteinase-9 (MMP-9), resulting in the protection of the latter from autodegradation." (PMID 40732340, 2025). "Restoring LCN2 expression significantly disrupted tumor growth induced by WTX-L knockdown in a subcutaneous tumor model." (PMID 40109379, 2025). "The aim of this study was to investigate the serum levels of transferrin and lipocalin 2 in Syrian breast cancer patients, and compare them with those in a control group and their correlation with the tumor state and characteristics." (PMID 40450119, 2025).